ARFGEF1 (ARF guanine nucleotide exchange factor 1)
Description:
Promotes guanine-nucleotide exchange on ARF1 and ARF3. Promotes the activation of ARF1/ARF3 through replacement of GDP with GTP. Involved in vesicular trafficking. Required for the maintenance of Golgi structure; the function may be independent of its GEF activity. Required for the maturation of integrin beta-1 in the Golgi. Involved in the establishment and persistence of cell polarity during directed cell movement in wound healing. Proposed to act as A kinase-anchoring protein (AKAP) and may mediate crosstalk between Arf and PKA pathways. Inhibits GAP activity of MYO9B probably through competitive RhoA binding. The function in the nucleus remains to be determined.
Synonyms: ARFGEP1; BIG1; DKFZP434L057; p200; DEDISB
Tractability: Small molecule: a structure with a bound ligand is known. PROTAC: ubiquitination databases record sites on it; its protein half-life has been measured.
Gene: Protein-coding gene on chromosome 8 (67,173,511 to 67,343,961, reverse strand). Ensembl gene ENSG00000066777.
Subcellular location: Cytoplasm; Cytoplasm, perinuclear region; Golgi apparatus; Golgi apparatus, trans-Golgi network membrane; Nucleus; Nucleus, nucleolus; Nucleus matrix
Subcellular location (Human Protein Atlas): Golgi apparatus; Cytosol; Nucleoplasm
Gene Ontology:
Molecular function: GTPase activator activity; guanyl-nucleotide exchange factor activity; myosin binding; protein binding; protein kinase A regulatory subunit binding
Biological process: endomembrane system organization; glycoprotein biosynthetic process; Golgi organization; negative regulation of actin filament polymerization; negative regulation of GTPase activity; positive regulation of wound healing; regulation of establishment of cell polarity; exocytosis; neuron projection development; positive regulation of phosphatidylinositol 3-kinase/protein kinase B signal transduction; regulation of ARF protein signal transduction
Cellular component: cytosol; Golgi apparatus; Golgi membrane; nuclear matrix; nucleolus; nucleoplasm; nucleus; perinuclear region of cytoplasm; small nuclear ribonucleoprotein complex; trans-Golgi network; cytoplasm
Genetic constraint (gnomAD): Loss-of-function variants: 35 observed, 196.95 expected, observed/expected ratio (o/e) 0.18, 90% interval 0.14 to 0.24. The upper end of that interval is the gene's LOEUF score, 0.24, which puts it in group 1 of 6, group 1 being the genes least tolerant of losing a copy. Missense variants: 1,155 observed, 2,009.3 expected, observed/expected ratio (o/e) 0.57, 90% interval 0.55 to 0.6. Synonymous variants: 630 observed, 681.74 expected, observed/expected ratio (o/e) 0.92, 90% interval 0.87 to 0.99.
Homologues: Orthologues: chimpanzee ARFGEF1 (99% identical), macaque ARFGEF1 (99% identical), dog ARFGEF1 (99% identical), pig ARFGEF1 (98% identical), mouse Arfgef1 (97% identical), rat Arfgef1 (97% identical), guinea pig ARFGEF1 (95% identical), rabbit ARFGEF1 (95% identical), tropical clawed frog arfgef1 (88% identical), zebrafish arfgef1 (86% identical), Drosophila melanogaster Sec71 (59% identical), Caenorhabditis elegans agef-1 (42% identical), and 4 more. Paralogues in human: ARFGEF2 (74% identical), GBF1 (19% identical), IQSEC2 (12% identical), IQSEC1 (11% identical), MON2 (10% identical), IQSEC3 (10% identical), CYTH3 (9% identical), CYTH1 (9% identical), CYTH4 (9% identical), CYTH2 (9% identical), PSD3 (7% identical), PSD (7% identical), and 3 more.
Diseases named in the same sentence as ARFGEF1 in open-access papers:
ARFGEF1 is named in the same sentence as 19 diseases in open-access papers, as found by Europe PMC text mining. Sharing a sentence is not in itself a finding about the gene and the disease. The quoted sentences say what the papers report.
developmental delay (4 papers, 2022 to 2024). "Mono-allelic loss-of-function variants in ARFGEF1 have recently caused a developmental delay, intellectual disability, and epilepsy, with varying clinical expressivity." (PMID 35782386, 2022). "(2021) reported that haploinsufficiency of ARFGEF1 gene can cause developmental delay." (PMID 37139670, 2023). "The mother of probands 3 showed several features consistent with the ARFGEF1-related phenotype, including mild developmental delay and mild ID." (PMID 35782386, 2022).
colon cancer (3 papers, 2019 to 2023). "In colon cancer cells, ARFGEF1 is one of the targets of miR-27b in regulating cell proliferation." (PMID 36979661, 2023). "The miR-27b/ARFGEF1 axis represses colon cancer progression." (PMID 35048795, 2022). "miR-27b interacts with ARFGEF1 and inhibits ARFGEF1 expression in colon cancers." (PMID 35048795, 2022).
breast carcinoma (2 papers, 2017 to 2023). "Brefeldin A-inhibited guanine nucleotide-exchange protein 1 (ARFGEF1) was found to be downregulated in breast cancer." (PMID 36979661, 2023).
epilepsy (2 papers, 2017 to 2022). A brain disorder characterized by episodes of abnormally increased neuronal discharge resulting in transient episodes of sensory or motor neurological dysfunction, or psychic dysfunction. "Our study shows that disruption of Arfgef1 leads to the glutamate hypersensitivity in neurons and also apoptosis of DL neurons in the brain, which might help to explain the mechanism of damage in epilepsy caused by Arfgef1 mutation." (PMID 28414797, 2017).
cervical cancer (1 paper, 2022). A primary or metastatic malignant neoplasm involving the cervix. "We further verified the underlying mechanism of the miR-133b/ARFGEF1 axis in cervical cancer." (PMID 35048795, 2022). "miR-133b targets ARFGEF1 to inhibit proliferation, invasion, and migration in cervical cancer cells." (PMID 35048795, 2022). "Herein, we revealed the interaction between miR-133b and ARFGEF1 in cervical cancer, as both bioinformatics online analysis and dual luciferase reporter assay confirmed that ARFGEF1 was the direct target gene of miR-133b." (PMID 35048795, 2022). "All results revealed that miR-133b suppresses cervical cancer progression by inhibiting proliferation, invasion, and migration of cervical cancer cells via targeting ARFGEF1." (PMID 35048795, 2022). "miR-133b expression was decreased, and ARFGEF1 was up-regulated in tumor tissues of cervical cancer patients (P < 0.05)." (PMID 35048795, 2022). "Moreover, the expression levels of miR-133b and ARFGEF1 were measured in patients with cervical cancer." (PMID 35048795, 2022). "Here, we verified whether miR-133b could affect the development of cervical cancer by targeting ARFGEF1." (PMID 35048795, 2022). "Finally, the mRNA and protein expression of miR-133b and ARFGEF1 in the tumor and adjacent normal tissues of cervical cancer patients was detected by real-time quantitative PCR, Western blotting, and immunohistochemistry." (PMID 35048795, 2022). "Therefore, overexpression of ARFGEF1 weakens the influence of miR-133b on the proliferation, invasion, and migration ability of cervical cancer cells." (PMID 35048795, 2022). "Furthermore, the role of the miR-133b/ARFGEF1 axis in the progression of cervical cancer was elucidated, providing a theoretical basis for clinical treatment of cervical cancer." (PMID 35048795, 2022). "Thus, we confirmed that tumor tissues of cervical cancer patients display a down-regulation of miR-133b and an up-regulation of ARFGEF1." (PMID 35048795, 2022). "Thus, this work reveals the molecular mechanism of the miR-133b/ARFGEF1 axis in cervical cancer and suggests novel insight for the treatment of cervical cancer." (PMID 35048795, 2022). "Finally, we compared the expression of miR-133b and ARFGEF1 between tumor tissues and adjacent normal tissues in cervical cancer patients." (PMID 35048795, 2022). "Thus, we reasonably speculated that miR-133b could regulate cervical cancer progression by targeting ARFGEF1." (PMID 35048795, 2022). "However, the function of ARFGEF1 in cervical cancer is still unclear." (PMID 35048795, 2022). "Thus, our study determined the mechanism of miR-133b in cervical cancer, and confirmed miR-133b/ARFGEF1 may become a potential therapeutic target for cervical cancer." (PMID 35048795, 2022).
epileptic encephalopathies (1 paper, 2017). "Recently, a genetic screening with human as subject had shown that the mutation in Arfgef1 is one of the possible causes for epileptic encephalopathies." (PMID 28414797, 2017).
Kaposi's sarcoma (1 paper, 2023). A malignant neoplasm characterized by a vascular proliferation which usually contains blunt endothelial cells. "Moreover, in Kaposi’s Sarcoma induced by KSHV (Kaposi’s sarcoma-associated herpes virus) circulating ARFGEF1 was found to be significantly overexpressed and associated with induced cell migration, proliferation and angiogenesis." (PMID 36979661, 2023).
neurofibromatosis type 1 (1 paper, 2019). A clinically heterogeneous, neurocutaneous genetic disorder characterized by cafe-au-lait spots, iris Lisch nodules, axillary and inguinal freckling, and multiple neurofibromas. "Most significant enrichment was observed for NF1 (P = 0.000477, OR = 22.8), the gene causal for neurofibromatosis type 1 (NF1), followed by TRPM5, AP5B1, DNMT3L and ARFGEF1." (PMID 31175295, 2019).
osteosarcoma (1 paper, 2022). A usually aggressive malignant bone-forming mesenchymal neoplasm, predominantly affecting adolescents and young adults. "miR-376 c acts as a tumor suppressor in osteosarcoma by repressing proliferation, invasion, and differentiation via Wnt family member 3 (Wnt-3) and ARFGEF1 signaling pathways." (PMID 35048795, 2022).
prostate carcinoma (1 paper, 2024). A carcinoma that arises from epithelial cells of the prostate gland. "Noteworthy proteins upregulated in our dataset (case definition 1) and in the prostate cancer literature included cofilin 1 (CFL1) and Brefeldin-A-inhibited guanine nucleotide-exchange protein 1 (ARFGEF1)." (PMID 39125581, 2024).
tumor (7 papers, 2011 to 2023). "- circ_0059354 induces cancer development through overexpression of ARFGEF1 by targeting miR-766-3p and also circ_0059354 deficient inhibits tumor growth.- miR-766-3p acts as tumor suppressor miRNA by targeting ARFGEF1." (PMID 37205191, 2023). "In particular, our analysis highlighted ARHGAP5 and ARFGEF1 as previously unreported putative driver genes of tumor progression in this cancer type." (PMID 32732999, 2020). "miR-27b downregulates ARFGEF1, leading to tumor growth suppression." (PMID 36979661, 2023). "MiR-27b overexpression inhibited tumor growth, cell adhesion, and invasion by modulating ARFGEF1 and paxillin/c-Src axis, in HCT116 cells, and suppressed proliferation and migration in cancer stem cells by downregulating phospho-PI3K p110α and phospho-Akt expression." (PMID 36501111, 2022). "Investigation of genomic and transcriptional data identified only 2 genes (ARFGEF1 and PENK) whose copy number and expression differentiated 'metastatic' from 'non-metastatic' tumours, neither of which have been previously implicated in malignancy." (PMID 21385341, 2011).
cancer (6 papers, 2017 to 2023). A tumor composed of atypical neoplastic, often pleomorphic cells that invade other tissues. "For example, miR-215 exerts an anti-cancer effect in papillary thyroid cancer by modulating the epithelial-mesenchymal transition through the inhibition of its target, ARFGEF1." (PMID 35048795, 2022). "Previous research has demonstrated that ARFGEF1 functions as a target of miRNAs and takes part in various cancers." (PMID 35048795, 2022). "Furthermore, ARFGEF1 also has a crucial role in various cancers." (PMID 35048795, 2022). "As illustrated in the results section, three interconnected proteins, ARFGEF1, PLD2, and RPTOR, were successively activated, stimulating the cancer driver mTOR SP." (PMID 29062084, 2017). "In terms of major cancer-related proteins among SM-specific hubs, NOTCH1, ARFGEF1, PLD2, and RPTOR were strongly aligned with hallmarks of NSCLC." (PMID 29062084, 2017).
neurodevelopmental disorder (1 paper, 2022). A behavioral and cognitive disorder with onset during the developmental period that involves impaired or aberrant development of intellectual, motor, or social functions. "In this study, we searched the local Chigene database for ARFGEF1 mutations to establish an unquestionable causal link between ARFGEF1 mutations and neurodevelopmental disorders." (PMID 35782386, 2022). "However, given the clinical heterogeneity and low-penetrance mutations of ARFGEF1-related neurodevelopmental disorder, the robustness of the gene-disease association requires additional evidence." (PMID 35782386, 2022). "In this article, we reported five new pediatric patients with ARFGEF1-related neurodevelopmental disorder and a comprehensive evaluation of the clinical and molecular results in all five cases." (PMID 35782386, 2022). "Finally, we broadened the genotypic spectrum of ARFGEF1-related neurodevelopmental disorder using data from our local Chigene database, identifying five novels heterozygous (likely) pathogenic variants." (PMID 35782386, 2022). "The missense mutation (p.Ile1180Arg) is a pathogenic mutation, which proves that the pathogenesis of ARFGEF1-related neurodevelopmental disorders may be the loss of function caused by frameshifting, nonsense, splicing, or rare missense mutation of key conserved residues." (PMID 35782386, 2022).
ARFGEF1 also shares sentences with these, for which no sentence is quoted: colorectal tumor (1 paper); infection (1); Intellectual disability (1); lymph node metastasis (1); metastatic disease (1); papillary thyroid cancer (1).